EPCAM (epithelial cell adhesion molecule)
Diseases named in the same sentence as EPCAM in open-access papers (continued):
Sharing a sentence is not in itself a finding about the gene and the disease.
cancer (continued). "The finding that EGF‐like domain of EpCAM was cleaved off in cells which have undergone EMT suggests this cleavage may be involved in the EMT process and the cancer stem cell properties of these cells." (PMID 26775583, 2016). "Indeed, EpCAM and CD147 were identified on the surface of cancer cell lines of colorectal (CRC), lung (NSCLC) and pancreas (PaCa) (data not shown)." (PMID 27127176, 2016). "Thirdly, we have used EpCAM as a cancer cell marker in the present study however EpCAM, is a non-specific marker of cancer cells." (PMID 27427978, 2016). "Heterogeneity in EpCAM expression and the lack of cancer type-specific markers in most cancers limits CTC quantification." (PMID 27711186, 2016). "Although EpCAM is considered to be a potential target for epithelial derived cancers, not all epithelial cancers over-express EpCAM enough to outflank adjacent normal tissue." (PMID 27842504, 2016). "By flow cytometry, EpCAM+ MPs were detected in 79% (34/43) of carcinoma pleurisies with 221 EpCAM+ MPs/μl compared to only 1 out of 27 patients with non-carcinoma malignant pleurisies with a very low number of EpCAM+ MPs (11 MPs/μl)." (PMID 26689993, 2016). "OCAb9-1 also specifically recognized recombinant human EpCAM/Fc chimera (960-EP, R&D Systems, Minneapolis, Minn, USA) and several human cancer cells, but not normal cells." (PMID 26317650, 2015). "In this study, significant difference of EpCAM overexpression was revealed between cancer nest with and without metastasis and 100% overexpression of EpCAM in metastatic tissues probed by SYL3C." (PMID 26687301, 2015). "Adecatumumab (MT201), a fully human IgG1 monoclonal antibody targeting EpCAM, has cancer cell-killing activity that is independent of K-Ras status." (PMID 26317650, 2015). "For EpCAM protein, it was overexpressed in 67 (56.8 %) cancer tissues, but only in 1 (8.3 %) nonneoplastic lung tissues." (PMID 26698569, 2015). "EpCAM is required for sequestration of CTC from blood by the VeridexTM CellSearch system by immunomagnetic isolation, and CK for staining and visualisation of the isolated cancer cells." (PMID 25957999, 2015). "All the sub-populations of cancer cells with overexpressed EPCAM, by definition, will intravasate, but not all of them will survive to the immune system control and not all of them will be able to extravasate and seed." (PMID 25978366, 2015). "Although it has been recently reported that EpCAM-negativity might refer to highly aggressive and invasive CTCs, the impact of EMT-like cancer cells on metastatic tumor spread still has to be unraveled." (PMID 26695635, 2015). "Generally, EpCAM is not found on tumors of mesodermal and ectodermal origin but on most, if not all, carcinomas." (PMID 25477371, 2015). "Epithelial markers (e.g., EpCAM) are expressed on carcinomas but absent on mesenchymal leucocytes, and are frequently used to enrich and/or distinguish cancer cells from normal blood cells." (PMID 26604322, 2015). "Human carcinoma cells expresses the epithelial cell adhesion molecule (EpCAM) on their surface while this molecule is absent from the surface of haematological cells." (PMID 26504857, 2015). "EpCAM and CD133 have been used as cancer stem cells (CSCs) markers in HCC." (PMID 24816638, 2014). "These dyes are taken up and accumulated by cancer cells through an active transport system independent of the conventionally employed epithelial surface marker (EpCAM)." (PMID 24551200, 2014). "By contrast, no IL-12 was detected upon treatment of co-cultures of iDCs and EpCAM- cancer cell lines with anti-EpCAM:CD40L, nor when EpCAM+ cells were treated with an scFv:CD40L fusion protein of irrelevant specificity." (PMID 24741998, 2014). "Furthermore, in co-culture experiments of iDCs with a panel of EpCAM+ cancer cell lines, treatment with anti-EpCAM:CD40L induced significant IL-12 production that was inhibited by the EpCAM blocking antibody." (PMID 24741998, 2014).
cancer (continued). "Alternatively it suggests the existence of epithelial-to-mesenchymal transition (EMT) phenomena with a higher number of circulating cancer cells lacking epithelial markers such as EpCAM or cytokeratins." (PMID 25105871, 2014). "The expressions of EpCAM, CD24, CD44, CD133, and CXCR4 antigens were membranous in carcinoma cells." (PMID 25240521, 2014). "EpCAM (also known as 17-1A, GA733-2, KSA, ESA, and EGP-40) is a homophilic, calcium-independent cell adhesion molecule of 39–42 kDa expressed on most normal and cancerous epithelial tissues, cancer stem cells, embryonic stem cells and germ cells." (PMID 23758908, 2013). "Investigators have not determined the relationship between EPCAM protein expression status in cancers and localization of an EPCAM germline deletion." (PMID 23938213, 2013). "While it has been suggested that the level of EpCAM expression be tested in cancer patients, there is no consensus on the method to be used." (PMID 23460885, 2013). "Thus, we evaluated the significance of cancer stem cell markers, including CD133, CD44, and EpCAM, in CLC." (PMID 23192764, 2013). "Our results revealed that the expression of PDGFRα and EpCAM was mutually exclusive in all cancer cell lines tested (data not shown)." (PMID 23990866, 2013). "While demonstrated to be effective in isolation of CTCs expressing the epithelial cells surface marker, EpCAM, significant experimental evidence is developing which suggests that potential CTCs are present in blood of cancer patients that do not express EpCAM." (PMID 23112954, 2012). "Subsequent comparison of selective epithelial, mesenchymal and cancer stem cell (CSC) markers between AD and NAD populations of CN and CR patients demonstrated an enhanced trend in mRNA expression of E-cadherin, EpCAM, STAT3 and Oct4 in the NAD population of CR patients." (PMID 23056490, 2012). "EpDT3-FI showed binding only to the RB cells and not to the Müller glial cells, indicating the cancer cell–specific expression of EpCAM." (PMID 23213278, 2012). "Like EpCAM, TROP2 has been an attractive immunotherapeutic target in cancer treatment." (PMID 22482828, 2012). "There is no clear evidence of the origin of cancer stem cells, and in the case of the breast tissue differentiation model, epithelial cell adhesion molecule (EpCAM) acts more like a progenitor cell than a stem cell." (PMID 23213278, 2012). "We could detect as few as 1 human cancer cell/1 ml blood when spiking cells of the MDA-MB-468 and KPL-4 line, which express high levels of EpCAM." (PMID 22591372, 2012). "EpCAM, CD44, CD166, CD133 are the cancer stem cell marker for colorectal cancer." (PMID 22082307, 2011). "Of note, both cell lines lack E-cadherin expression (due to promoter methylation), which is a common feature among carcinoma cell lines with low or absent EpCAM expression." (PMID 21281469, 2011). "In view of the novel role of EpCAM as an oncogenic signal transducer and cancer stem cell marker, it is important to establish the clinical significance of nuclear Ep-ICD in human cancers." (PMID 20579375, 2010). "Strikingly, EpCAM is only found in epithelial-derived cancers, i.e., carcinomas, but not in others, such as sarcomas, melanomas, or lymphomas." (PMID 19609345, 2009). "The present meeting review is focused on new data investigating the significance of EpCAM for cancer biology and therapy, and can therefore not adequately cover all presentations given at the symposium." (PMID 17211480, 2007). "EpCAM and the number of clusters containing 2 or more cells (Clusters > 2) showed statistically significant differences (p = 0.022 and p = 0.007, respectively) in slope between HR+ and HER2+ cancers, indicating different biomarker rates of change over time between the two receptor subtypes." (PMID 40867346, 2025).
cancer (continued). "PTMs of tight junction proteins, including epithelial cell adhesion molecule (EpCAM) and claudins, cytoskeletal proteins (vimentin, actins, and tubulins), HIF1α, EMT-TFs, and matrisome proteins (collagen, fibronectin, and metalloproteinases) modulate invasion and metastasis of cancer." (PMID 39860065, 2025). "Combined with the large number of CTCs harvested by negative depletion of WBCs from leukopaks, the multispectral CTC imaging platform will yield a highly quantitative single-cell assessment of epitope expression without biased selection for EpCAM-positive cancer cells." (PMID 39746954, 2025). "Importantly, in analogous experiments using PC3M.EpCAM-KO cells, EpCAM-ReTARGTPRvIL2 induced a similar increase in cancer cell lysis of ~15%, suggesting that EpCAM-ReTARGTPRvIL2 enhances cancer cell lysis irrespective of EpCAM expression." (PMID 40243928, 2025). "Interestingly, our data revealed a correlation between the presence of an EMT‐like cancer cell population and elevated levels of CA‐125, while no strong correlation was observed between CA‐125 levels and other EpCam+ cell populations." (PMID 40411295, 2025). "Moreover, ITGAV knockdown in EpCAM+ plastic cancer cells significantly reduced EMT induction in response to TGFβ and blocked the generation of mesenchymal EpCAMneg cancer cells, although cancer cells showed pSMAD3 induction upon TGFβ1 treatment and translocation of pSMAD2 to the nucleus." (PMID 39075581, 2024). "The identified membrane proteins serve as receptors (EPHB6, ACKR1, and EDNRB) or adhesion molecules (EPCAM) and may enhance antitumor immunity (TENM2 and CLEC‐10A); thus, they may contribute to enhanced mEHT‐induced cancer destruction through regulating the TME related immune response." (PMID 38217262, 2024). "APC-labelled anti-CD45mAB was used to gate remaining hematogenous cells, while multiple epithelial markers (EpCAM, EGFR, and Pan-Cytokeratin) and an epithelial–mesenchymal transition (EMT) marker (Vimentin) labelled with fluorescein isothiocyanate (FITC) were used to sort cancer cells." (PMID 38469233, 2024). "Interestingly, not all epithelial EpCAM+ cancer cells from MD/PD-SCCs switched to the mesenchymal state during cSCC growth, suggesting that this population is heterogeneous." (PMID 38914547, 2024). "Ligands such as Tumor Necrosis Factor-Related Apoptosis-Inducing Ligand (TRAIL), Frizzled 10 (FZD10) Protein, EpCAM Aptamer, Programmed Cell Death Protein 1 (PD-1), RGD, CC-9 and RH-20, and specific DNA sequences have demonstrated enhanced uptake by cancer cells and cytotoxicity." (PMID 38543324, 2024). "In addition, the expression of EpCAM is low or absent in CTCs in certain cancers, e.g., EpCAM-negative CTCs in metastatic breast cancer." (PMID 38791091, 2024). "As expected from a homogeneous cancer cell composition, no changes in the relative content of epithelial EpCAM+ and mesenchymal EpCAM− cancer cells vs. total cancer cells were observed after performing the ICB treatments on epithelial and mesenchymal mouse cSCCs." (PMID 38914547, 2024). "Also, spatial analysis identified cells positive for the cancer stem cell (CSC) markers, CD44v6 and EpCAM, within these cellular neighborhoods that could contribute to stemness, drug resistance, and metastasis." (PMID 39356141, 2024). "Although EpCAM-based CTC detection has shown great promise across many types of cancers, this method may not capture CTCs which have undergone an epithelial-to-mesenchymal transition (EMT) since they may not express EpCAM." (PMID 38780775, 2024). "However, recent research indicates that EPCAM-negative CTCs also participate in the distant metastasis of cancer cells, indicating the need for alternative biomarkers for identification and isolation of CTCs." (PMID 37720505, 2023).
cancer (continued). "In addition, it is reported that the use of epithelial cell adhesion molecule, EpCAM CAR-T cells, could foster cytokine release (i.e.,: interferon-γ, IL-2, and IL-6), which in turn induces strong apoptotic effects on cancer cells." (PMID 36831396, 2023). "In this study, we isolated CTCs from prostate (n = 17) and pancreatic (n = 5) cancer patients using a disposable lateral magnetophoretic microseparator, comparing the isolated CTC count, white blood cell (WBC) depletion rate, and CTC purity based on the EpCAM and vimentin antibodies combination." (PMID 37345161, 2023). "Thus, EpCam expression parallels EMT, cancer metastasis and presence of other stemness markers." (PMID 37108193, 2023). "EpCAM, whose overexpression has been linked to PCA progression, was used to label and characterize cancer-derived cells but was not used for sorting, as we could not exclude the presence of PCa cells expressing low levels of this marker." (PMID 37345004, 2023). "HNSCC is an epithelial-originated cancer, but in reality, EpCAM is not always present in every CTC derived from HNSCC cases due to the transition between epithelial and mesenchymal characteristics, which results in the high specificity but low sensitivity of the current detection methods." (PMID 36980712, 2023). "EpCAM-based methods may have limitations for aggressive cancers, as sometimes they do not exhibit EpCAM expression." (PMID 37654932, 2023). "However, lack of EpCAM expression in PZP cells suggest that they are not the “normal counterparts” of cancer stem cells." (PMID 37709737, 2023). "Further analysis of TAM-stimulated primary cancer cell clusters compared to naïve cell clusters revealed that c-Myc, PLAU, PLAUR, and AXL were significantly upregulated, while the downregulated epithelial marker (EPCAM) was observed in the disseminated cell clusters." (PMID 35680853, 2022). "As a general feature, the expression of epithelial genes (e.g. TJP3, TSPAN13, CLDN7 and EPCAM) was positively correlated with the expression of AGR2/3 and the expression of mesenchymal genes (e.g. VIM and MSN) was negatively correlated, with specific correlations according to cancer type." (PMID 35857928, 2022). "Catumaxomab, a hybrid mouse IgG2a/rat IgG2b antibody that is trispecific for EpCAM, CD3, and, via the Fcc receptor, that activates accessory cells such as macrophages, NK cells and DCs, obtained market approval in Europe in 2009 to treat malignant ascites in cancer patients." (PMID 35207472, 2022). "Additionally, we studied the effects of the changes in the expressions of EpCAM and E-cadherin, and also those of other important proteins (Akt, ERK1/2, Nanog, Oct-4, and β-catenin) involved in the EMT, and the proliferation and/or migration of cancer cells." (PMID 35159188, 2022). "Thus, although cancer patients can be distinguished from healthy donors based on the presence of EpCAM+EGFR+ cells, patients with benign inflammatory colon diseases could be misclassified as cancer patients." (PMID 36613466, 2022). "Additionally, this double positive population from samples in the cancer group expressed higher levels of EpCAM, though not panCK, compared to the cells of the same quadrant that belonged to samples from the high-risk group." (PMID 35976857, 2022). "DAVID functional annotation had selected only 4 out of 16 pathways in the A549 CD166 + EpCAM + CSC subpopulation, and 3 pathways in the A549 CD166-EpCAM– non-CSC subpopulation that were related to cancer diseases and that involved the proteins YWHAB, YWHAQ, and YWHAZ." (PMID 33670440, 2021). "More importantly, we also explored the cell stemness of six-FBXOs in PDAC by using the GSE51971 dataset, whose data were classified into triple-positive group and triple-negative group according to whether these expressed the three important cancer stem cell markers, CD44, CD133, and EpCAM." (PMID 35046938, 2021).
cancer (continued). "In this work, EVs from three different cancer types were captured with anti-CD63 magnetic beads, followed by the addition of three types of SERS nanotags (i.e. Raman reporter-detection antibody-decorated AuNPs targeting the EV membrane proteins glypican-1, EpCAM, and CD44)." (PMID 34855021, 2021). "For example, in lung stem-like cancer cells that display positivity of CD166, together with CD44 and EpCAM, the cells were found to be more sensitive to NFκB inhibitors for suppressing the expression of CD166, suggesting a strategy to target this small population of cancer cells for treatment." (PMID 34680335, 2021). "The CellSearch platform is a method of EpCAM-based rare cell capture technology (RCCT), which uses an immunomagnetic CTC selection using EpCAM antibody conjugated ferroparticles, able to provide a quantitative assessment of cancer cells in a limited amount of CSF (3 cc)." (PMID 34207653, 2021). "During EMT, EpCAM can also be cleaved during a process called regulated intramembrane proteolysis (RIP) and its intracellular domain (EpICD) is transported into the nucleus and helps to stimulate target gene transcription that promotes growth, cancer stem cell properties, and EMT." (PMID 34209658, 2021). "Increased expression of PAI-1 subsequent to HCV infection promoted the cancer stem-like cells (CSC) state in HCV-infected hepatocytes through the activation of the chief mediator of cell proliferation, protein kinase B, in consort with the increased expression of the CSC marker, EpCAM." (PMID 35070966, 2021). "However, the markers used to detect CTC are not carcinoma-specific as they identify epithelial cells in general, e.g., cytokeratins or epithelial cell adhesion molecule (EpCAM)." (PMID 35008210, 2021). "Thus, a capture technique, which is independent of epithelial markers, such as EpCAM, would be desirable to target a broad range of cell states or cancer entities." (PMID 32244341, 2020). "We focused on biomarkers that exhibit the various hallmarks of cancer, and for which NIRF probes are already clinically available: epidermal growth factor receptor (EGFR), vascular endothelial growth factor-A (VEGF-A), integrin αvβ6 and epithelial cell adhesion molecule (EpCAM)." (PMID 32545676, 2020). "The ability to detect and enumerate EpCAM low/negative CTCs are vital because these could facilitate for better predictions on the cancer stages, patients prognosis as well as designing the ideal therapeutic strategy and management of the patients care." (PMID 32046162, 2020). "Furthermore, neither regulated intramembrane proteolysis of EpCAM nor EPCAM knockout in cell lines had any measurable impact on cell-matrix and cell-cell adhesion in cancer cells." (PMID 32507912, 2020). "A plethora of new technologies emerged to overcome the limitations of EpCAM-based approaches, focusing on the challenge of detecting non-epithelial CTCs, mainly exploiting mesenchymal markers or physical features of cancer cells and other cancer-specific traits." (PMID 32325824, 2020). "A critical component in cancer progression is epithelial–mesenchymal transition (EMT), during which tumor cells lose intercellular adhesions, downregulate epithelial molecules (e.g., EpCAM), and up-regulate the expression of mesenchymal molecules, such as N-cadherin and vimentin." (PMID 32182935, 2020). "The presence of CTCs has been shown to be limited in EC, and a small number of high-risk patients, mainly those with non-endometrioid high grade carcinomas, have been identified with Epithelial Cell Adhesion Molecule (EpCAM) positive CTCs in circulation at the time of diagnosis." (PMID 32098121, 2020). "For unknown reasons, the reported cleavage of EpCAM following EGF treatment could not be reproduced in a variety of carcinoma cell lines." (PMID 32507912, 2020). "However, recent experiments failed to prove the oligomerization of EpCAM protein in vitro and the role of EpCAM in adhesion in carcinoma cells." (PMID 33029133, 2020).